IL6 (interleukin 6)
Diseases named in the same sentence as IL6 in open-access papers (continued):
Sharing a sentence is not in itself a finding about the gene and the disease.
Obesity (continued). "In summary, IL-6 deficiency does not protect against early postnatal obesity but prevents FoxO1 inactivation and bronchial and lung microvascular SMC hyperproliferation, thereby preventing bronchial and vascular remodeling after maternal and perinatal obesity." (PMID 35896539, 2022). "Collectively, these findings suggest that Phillyrin can restrain lipid efflux from inflamed adipose tissue in obesity by inhibiting IL-6-initiated basal lipolysis and ATGL expression, and thus is a potential candidate in the treatment of obesity-associated complications." (PMID 36276810, 2022). "Moreover, 98.2% of the change in leptin is due to the changes in IL-6, IL-12, serotonin, and BW as markers of inflammation, brain chemistry, and obesity respectively." (PMID 36364892, 2022). "These proinflammatory markers may be a direct source or a consequence of obesity, particularly IL-1β, IL-6, and TNF-α, which are associated with chronic and acute inflammation related to obesity." (PMID 36304965, 2022). "Interestingly, gallic acid exerts protective effects against obesity-related inflammation by reducing adipocyte size and the inflammation markers, as IL-6, NOS and COX2." (PMID 35204243, 2022). "Previous studies demonstrated that IL-6 triggers hepatic insulin resistance by inhibiting insulin signaling in vivo and in vitro and could thereby be involved in obesity-related hepatic insulin resistance." (PMID 35628414, 2022). "In addition, TNF-α and IL-6 mainly came from adipose tissue, which were significantly increased in adults with MetS as they were positively correlated with the degree of obesity." (PMID 35433780, 2022). "Additionally, it has been shown that the release of the IL-6 and IL-8 cytokines in metabolic disorders, such as obesity, is increased to mediate the crosstalk between adipocytes and BC cells within the tumor microenvironment." (PMID 35927653, 2022). "In addition, due to the clear link between obesity and cataract caused by chronic inflammation and inflammatory markers such as CRP, IL-6 and TNF-α, and urinary isoprostanes, it is apparent that obesity is a risk factor contributing to cataract." (PMID 35565652, 2022). "Obesity has a strong association with immune cell abnormalities, and adipose tissue produces and releases various adipokines (leptin, adiponectin, resistin and visfatin) and pro-inflammatory cytokines (TNF-α, IL-4, IL-6)." (PMID 36574392, 2022). "Similarly, at the visceral adipose tissue level, HFD-induced obesity led to an up-regulation of the production of IL-1β, IL-6, TNF-α and MCP-1 as well as leptin and adiponectin." (PMID 35624723, 2022). "Although there are many controversial studies on the effects of IL-6 on obesity, IL-6 must be the key in the process of energy metabolism and adipogenesis, which may involve pathways like IL-6/STAT3/AMPK and IL-6/STAT3/PPARγ." (PMID 36105933, 2022). "Furthermore, the increase in IL-6 levels observed during obesity can result in a 75% decrease in adiponectin secretion, as shown in 3T3-L1 adipocytes." (PMID 35628332, 2022). "The increased levels of IL-6 in obesity may act as a compensatory mechanism to improve insulin resistance instead of inducing chronic low-grade inflammation." (PMID 36452038, 2022). "As patients with obesity suffer from a chronic low-grade pro-inflammatory state in which plasma levels of pro-inflammatory cytokines such as IL-6 are elevated, we explored whether IL-6 signaling mediates the association between BMI and risk of MS." (PMID 35386698, 2022). "Increased visceral adiposity has been reported to lead to decreased testosterone levels, by yet not completely understood mechanisms, involving hypothalamic inflammation and decreased GnRH release and/or obesity-related metabolic endotoxemia-induced IL-6 release, inhibiting testicular function." (PMID 35135482, 2022).
Obesity (continued). "Notably, each advanced age and obesity resulted in enrichment of IL-6/JAK/STAT3 signaling, which cultivates an immunosuppressive environment by stimulating expansion of myeloid-derived suppressor cells and controlling antitumor T cell responses." (PMID 36686775, 2022). "Furthermore, cytokines' release, such as tumor necrosis factor (TNF) and interleukin-6 (IL-6), is elevated, which is produced from the activated macrophages of the adipose tissue during obesity." (PMID 36304965, 2022). "Obesity has been linked to increased production of several cytokines, including C-reactive protein (CRP), tumor necrosis factor alpha (TNF-α), and interleukin-6 (IL-6)." (PMID 35941593, 2022). "In addition to adipokines such as leptin, M1-type macrophages recruited by hypertrophy or dysfunctional adipose tissues in obesity further secrete proinflammatory cytokines including TNFα and IL-6, which can regulate hepcidin expression." (PMID 36335331, 2022). "In addition, the gut microbiota influenced inflammatory factors by modulating the secretion of inflammatory cytokines, and IL-6 and TNF-α are the biomarkers associated with inflammation and obesity." (PMID 35579462, 2022). "Human obesity, characterized by the expansion of adipose tissue, is considered a condition of a low-grade chronic inflammatory state characterized by the elevation of well-known inflammatory cytokines, such as TNFα and IL-6 within plasma." (PMID 35335277, 2022). "Both drugs have proven to be effective in reducing inflammation through various pathways: they reduced CRP levels in patients with obesity, while colchicine was also effective in reducing IL‐6, IL‐16, resistin, complement proteins C5a and C9, and the activity of the COX‐2 enzyme." (PMID 35837843, 2022). "Moreover, significant upregulation of the in IL-6 mRNA was detected (P = 0.006) in IBC patients with obesity who had lymph node (LN) metastasis (n = 10) when compared with the non-IBC group (n = 17) for which its expression was not changed (P = 0.324)." (PMID 35927653, 2022). "Osteoporosis, obesity, and sarcopenia have been studied extensively as individual conditions, and strong evidence has been uncovered for the roles of inflammatory cytokines, such as IL-6, IL-1, and TNF-α, in their pathogenesis." (PMID 35764967, 2022). "In addition to inflammation (IL-6), obesity (BMI), and malnutrition (SGA), overhydration contributed to low LTI." (PMID 36036423, 2022). "We have shown IL-6 as a potential mediator linking obesity and asthma." (PMID 36253437, 2022). "Moreover, the exercise-induced reduction of visceral AT mass is abolished in patients with obesity when IL-6 signaling is blocked, suggesting that IL-6 is required for the exercise-mediated reduction of visceral AT mass." (PMID 35909571, 2022). "Regarding the inflammatory markers, the chronic inflammatory state in obesity could explain the increased levels of IL-6 and their association with FGF21, as roughly 30% of circulating IL-6 is derived from adipose tissue." (PMID 35207221, 2022). "Pharmacological blockade of mitoSTAT3 either by a mitochondria-targeted STAT3 inhibitor or ROS scavenging prevented obesity and fatty acid–induced production of proinflammatory cytokines IL-17A and IL-6, thus establishing a mechanistic link between mitoSTAT3 and inflammatory cytokine production." (PMID 35928250, 2022). "At the same time, IL-6 will in turn affect obesity, but its mechanism is relatively complex." (PMID 36105933, 2022). "Likewise, low-grade chronic inflammation associated with obesity and the subsequent increase in pro-inflammatory cytokine secretion is associated with insulin resistance, with TNF-α, IL-1β, and IL-6 directly impairing insulin signal transduction." (PMID 35883605, 2022).
Obesity (continued). "Due to the clinical features of obesity and abdominal obesity, it may have higher levels of inflammatory cytokines and adipokines (eg, interleukin-1, interleukin-6, C-reactive protein, tumor necrosis factor alpha)." (PMID 35846319, 2022). "We attribute our findings to the fact that we were able to exclude patients with chronic inflammatory diseases and severe obesity, which are major confounders when studying sub-clinical vascular inflammation as there is a strong relationship (rho = 0.85; p < 0.00001) between IL-6 levels and BMI." (PMID 36028849, 2022). "Notably, aside from the debated role of IL-6 in obesity and insulin resistance, other members of the IL-6 family of cytokines, including CT-149, are oversecreted in obesity and affect the energy balance." (PMID 35585213, 2022). "In humans, increased circulating MCP-1 correlates with higher levels of other inflammatory markers such as C-reactive protein (CRP) and interleukin-6 (IL-6), but also obesity, waist circumference, and the homeostatic model assessment for insulin resistance (HOMA-IR) score." (PMID 36106024, 2022). "Furthermore, TNF-α and IL-6 were more likely to be downregulated in DIO mice with periodontitis when compared with their obesity-only counterparts." (PMID 36060644, 2022). "In obesity, oxidative stress linked with alteration of the immune system and with ultimate aberrant cell signaling, stimulated cell growth and angiogenesis is promoted via enhanced inflammatory factors and adipokines (TNF, leptin, IL-1β, and IL-6)." (PMID 35628513, 2022). "Univariate logistic regression identified a significant relationship between odds for undetectable baseline E1 and presence of high-risk IL-6 promoter (OR 0.17, p = 0.05) but not by obesity (OR 0.97, p = 0.50)." (PMID 36369506, 2022). "Moreover, treatment of neuronal cells with the inflammatory molecules TNF-α and IL-6, which are also induced within the metabolic environment of obesity, activates syncytin-1 gene expression." (PMID 35444566, 2022). "Similarly, IL-6 levels were frequently elevated in obese subjects and positively correlated with obesity in human populations." (PMID 36387880, 2022). "Therefore, we selected IL-6, which is highly relevant among the hub genes screened, as an entry point to uncover the mechanism by which acupuncture regulates inflammation to affect obesity and suggested the importance of IL-6 in the prognostic of PAAD." (PMID 36105933, 2022). "HFD-induced obesity of rats also caused systemic inflammation with an elevation of serum CRP levels and a significant increase in the serum levels of the inflammatory cytokines IL-6 and TNF-α." (PMID 35721744, 2022). "However, the elevation of systemic IL-6, often in obesity and metabolic syndrome, and the role of IL-6 in metabolic disease remains controversial." (PMID 36552772, 2022). "Thus, it is possible that increased IL-6 production in obesity and aging additively contributes to peripheral Treg accrual in both male and female mice." (PMID 34099626, 2021). "Nevertheless, IL6 might express also an anti-inflammatory activity mediated by classic signaling mode, while the proinflammatory role identified in the setting of obesity is mediated by the trans-signaling pattern." (PMID 34207683, 2021). "In addition, obesity promotes liver inflammation and tumorigenesis by enhancing the expression of interleukin-6 (IL-6) and tumor necrosis factor (TNF), which further activates several pro-oncogenic pathways." (PMID 35154012, 2021). "Following exercise, IL-6 circulating levels increase and stimulate the IL-10 anti-inflammatory cytokine, and finally, inflammatory cytokines may act as a response to prevent obesity by modulating both energy intake and consumption." (PMID 33997019, 2021).
Obesity (continued). "In obesity, excessive fat accumulation in adipose tissues promotes chronic low-grade inflammation related to produce a variety of pro-inflammatory cytokines, such as interleukin-6 (IL-6), interleukin-1β (IL-1β) and tumor necrosis factor-α (TNF-α)." (PMID 34681074, 2021). "It would be fascinating to clarify whether obesity shares with lipolysis this mechanism to regulate IL-6 production in adipocytes." (PMID 34504646, 2021). "FER tyrosine kinase increases NF-κβ activation and signals interleukin-6 (IL-6) to regulate STAT3 phosphorylation, which may explain its relationship with breast cancer risk through adiponectin and obesity." (PMID 34367982, 2021). "In addition to the reduced number and imbalanced subgroups, functional defects of B cells in individuals with obesity possibly participate in the formation of cytokine storm by secreting more pro-inflammatory cytokines (e.g., IL-6)." (PMID 34373739, 2021). "First of all, both obesity and lipolysis induced a surge in IL-6 in adipose tissue in mice." (PMID 34504646, 2021). "Thus, high levels of plasma IL6 are correlated with obesity, type 2 diabetes and even with the prediction of this pathology, and it decreases with the loss of adipose tissue and body weight." (PMID 35111744, 2021). "Furthermore, EA ameliorated obesity-associated inflammatory responses through decreasing area neutrophil+, area CD11b+, area F4/80+, F4/80 mRNA, TNF-α mRNA, MCP-1 mRNA, CD68 mRNA, and IL-6 mRNA in adipose tissues." (PMID 35095910, 2021). "Our findings suggest that obesity plays a role in chronic inflammation (as seen in leptin and IL-6 levels modified by BMI) while the additional inflammatory pressure resulting in elevated NOV and EPC levels is likely driven by intermittent hypoxia and inflammation specific to OSA pathophysiology." (PMID 34868456, 2021). "Elevated levels of PAI-1 and IL-6 are characteristics of obesity and type-2 diabetes." (PMID 34777426, 2021). "Finally, interleukin 6 will activate the hypothalamic-pituitary-adrenal axis, which will contribute to the onset and maintenance of atherosclerosis, hypertension, obesity, and insulin resistance." (PMID 34683106, 2021). "A mechanism study demonstrated that TNF-alpha and IL-6 can enhance HCC in NAFLD or obesity population, which could be activated by the elevated ER stress in NAFLD patients." (PMID 33868403, 2021). "Adipose tissue hyperplasia during obesity induces the secretion of adipocytokines such as leptin, interleukin-6 (IL-6), interleukin-1β (IL-1β), IL-10, TNF-α, monocyte chemo-attractant protein-1, and plasminogen activator inhibitor-1, which are responsible for obesity-related inflammation." (PMID 33946303, 2021). "Similarly, high levels of IL-6 and IL-15 have been detected in the salivary samples of children with obesity." (PMID 35601749, 2021). "IL-6 is secreted from adipose tissue and is known to be elevated in obesity and insulin resistance." (PMID 34266493, 2021). "IL-6 is a pleiotropic cytokine with diverse effects, and its elevated levels are routinely mentioned to signify inflammation associated with pathophysiology of several conditions including CKD and obesity." (PMID 34168254, 2021). "Changes in the production of adipokines such as leptin, resistin, lipocalin 2, tumor necrosis factor-α, chemerin, retinol binding protein 4, and interleukin-6 have been reported in obese individuals, and this can lead to the development of obesity-related metabolic diseases." (PMID 33498329, 2021). "Inflammatory cytokines such as TNF-α and IL-6, highly abundant in obesity and T2D, bind to receptors on the cardiomyocyte surface which triggers downstream activation of NF-κB and other central regulators of cell metabolism with differential impact on cardiomyocyte function." (PMID 34671656, 2021).
Obesity (continued). "It has been suggested that chronic inflammation in obesity is apparent, with an increased level of interleukin-6, adipokines and pro-inflammatory cytokines (e.g., TNF-alpha, interferon), inducing a chronic low-grade inflammatory state and impairing immune response." (PMID 33556150, 2021). "Interestingly, people suffering from obesity have also been reported to have an increased production of proinflammatory cytokines such as IL-6." (PMID 33867858, 2021). "Obesity and metabolic syndrome are accompanied by persistently increased IL-6 and TNF-α levels which may contribute to insulin resistance and deleterious vascular effects." (PMID 34202323, 2021). "Interestingly, the blockage of Fas signaling can attenuate obesity-induced adipose tissue inflammation by inhibiting IL-6 whilst promoting IL-10 secretion." (PMID 33808960, 2021). "In addition to these analytes, and as previously reported, pregravid obesity resulted in significantly higher levels of IL-6 and CRP both at T1 and T3, highlighting a state of chronic low-grade inflammation." (PMID 34195568, 2021). "Obesity in adolescents can be accompanied by dyslipidemia, insulin resistance (IR) and chronic low-grade inflammation, with increased levels of proinflammatory cytokines such as IL-6." (PMID 34065056, 2021). "Here, we showed that obesity-resistant mice express larger amounts of IL6 than obesity-prone mice." (PMID 34465367, 2021). "In asthma, elevated serum IL-6 has been found to be associated with lower pulmonary function and greater exacerbation risk, independent of obesity." (PMID 34835964, 2021). "In obesity, the main source of IL-6 is the visceral adipose tissue." (PMID 34202323, 2021). "So what is the ultimate effect of adipose IL-6 on inflammation in obesity?" (PMID 34504646, 2021). "Adipose tissue has been shown to produce 10–35% of IL-6 in a resting individual, and this production increases with increased adiposity, indicating that adipose tissue is a source of the increased circulating IL-6 observed in obesity." (PMID 34831450, 2021). "No relation was found between obesity parameters and IL-6 polymorphisms rs1800795, rs1800796 and rs13306435." (PMID 34680892, 2021). "The inflammatory response in non-type 2 asthma is dominated by type 1 and/or type 17 T-cell and many of these asthmatics suffer from comorbidities, including obesity, glucose dysregulation and hypertension as part of the metabolic syndrome, characterized by higher plasma levels of IL-6." (PMID 33804084, 2021). "Additionally, adipose tissue can also synthesize cytokines such as TNF-∝ and IL-6 thus obesity itself promotes inflammation and potentiates atherogenesis." (PMID 33841183, 2021). "Thus, we postulated a positive feedback loop between ATM and adipocytes via IL-6 signaling backing ATM persistence by comparison of ATM remodeling under obesity and lipolysis." (PMID 34504646, 2021). "IL-6 can adapt the metabolism to physical exercise and obesity during pro-inflammatory states." (PMID 34327205, 2021). "In obesity, production of IL6 is stimulated by both IL-1β and TNFA81." (PMID 33820928, 2021). "In the same perspective, IL-6, in adipose tissue, has pro-inflammatory characteristics, being directly related to the BMI, and is augmented in individuals with insulin resistance, obesity, and DM2." (PMID 33807959, 2021). "Obesity associates a non-TH2 subclinical inflammatory state induced by the infiltration of M1-type macrophages capable of liberating pro-inflammatory cytokines such as IFN-γ, IL-6, TNF-α, IL-1β and monocyte chemotactic peptide (MCP)-1." (PMID 34836093, 2021). "IL-6 may also be involved in obesity-related insulin resistance: plasma IL-6 levels positively correlated to weight gain in humans." (PMID 34830209, 2021). "Both positive and negative associations between obesity and IL-6 polymorphisms in multiple loci have been reported." (PMID 34680892, 2021). "In this regard, the role of IL-6 in the liver is of interest in obesity." (PMID 33579000, 2021).